TMPRSS2 (transmembrane serine protease 2)
Diseases named in the same sentence as TMPRSS2 in open-access papers (continued):
Sharing a sentence is not in itself a finding about the gene and the disease.
prostate carcinoma (continued). "The TMPRSS2-ERG fusion is present in approximately 50% of prostate cancers, while fusions with ETS genes ETV1, ETV4, and ETV5 occur in approximately 10%, 2 to 5%, and 1% of cases, respectively." (PMID 37956771, 2023). "Cell culture experiments revealed that the TMPRSS2 androgen-responsive promoter elements mediate the overexpression of ETS in prostate cancer." (PMID 37310937, 2023). "The up-regulation of ERG is observed in >50% of prostate cancer cases, due to a genetic fusion between trans-membrane serine protease 2 (TMPRSS2) and ERG." (PMID 37310937, 2023). "Despite the fact that TMPRSS2:ERG fusion is a frequently occurring molecular event in prostate cancer, its precise impact on the clinical aspects of the disease remains controversial." (PMID 37511059, 2023). "Overexpression of N-terminal truncated, but fully functional ERG due to ERG gene fusion with TMPRSS2 gene occurs in approximately 50% of prostate cancer (PCa) patients." (PMID 37537199, 2023). "Multiple studies have indicated that TMPRSS2 has the potential to be a valuable biomarker, mainly for the diagnosis of prostate cancer." (PMID 37511059, 2023). "Matriptase is synthesized as a zymogen, which can be activated via proteolytic cleavage by other proteases, for example by Tmprss2, enhancing its effect on the growth and invasiveness of prostate cancer." (PMID 37566613, 2023). "Its involvement in pathology includes priming viruses for cellular entry and upregulation in prostate cancer, and previous studies have shown that TMPRSS2’s transcription can be stimulated by androgens in the prostate but not in the lung." (PMID 36656980, 2023). "A similar mechanism is often present in prostate cancer, where the TMPRSS2::ERG oncofusion is found in roughly 50% of tumors and MAN2A1::FER, MTOR::TP52BP1, and SLC45A2::AMACR occur at lower frequencies." (PMID 37509339, 2023). "The most common genetic abnormality, present in 40–50% of prostate cancers, is the translocation of the transmembrane protease serine 2 to the v-ets erythroblastosis virus E26 oncogene (TMPRSS2-ETS)." (PMID 37511177, 2023). "TMPRSS2 is also involved in other types of cancer, such as prostate cancer, through its important role in cell invasion, tumor growth, and metastasis." (PMID 37610679, 2023). "TMPRSS2 is a type II transmembrane serine protease and was first identified in the context of prostate cancer (PCa)." (PMID 36834705, 2023). "The sensitivity and specificity of the EV-derived gene TMPRSS2-ERG used in the diagnosis of prostate cancer exceed 80%, indicating that prostate cancer can be detected without imaging, by using this liquid biopsy." (PMID 36911396, 2023). "We chose TMPRSS2:ERG fusion because this is the most frequent molecular alteration found in prostate cancer, and IHC data on AR expression because of its known interaction with PSAP." (PMID 37892063, 2023). "The PCR products obtained by amplification of the prostate cancer marker TMPRSS2-ERG on cDNA from the prostate cancer tissue (PCaT) and derived early PCCs and PDOs were cloned and sequenced." (PMID 36769153, 2023). "The association of ERG overexpression with specific histomorphologic features and prognosis in prostate cancer has been a topic of debate since the discovery of the TMPRSS2:ERG fusion." (PMID 37511059, 2023). "The TMPRSS2-ERG fusion gene was found to enhance the expression of plexin-B1 in prostate cancer cells." (PMID 37627074, 2023). "Transmembrane serine protease 2 (TMPRSS2) is a transmembrane protein primarily found in prostate’s secretory epithelium, prostate cancer cells, and in pancreatic and colon cancer specimens." (PMID 37021836, 2023). "ERG and TMPRSS2 fusion is found in about 50% of prostate cancers, and ETV1 and TMPRSS2 fusion is found in 5% of prostate cancers." (PMID 36289913, 2022). "The TMPRSS2-ERG fusion protein was showed to mediate prostate cancer cell invasion and activation of transcriptional programs for invasion-associated genes." (PMID 35547880, 2022).
prostate carcinoma (continued). "In the prostate cancer cell line LNCaP, the AR was found to bind to response elements present in approximately the first 80 kb upstream of TMPRSS2." (PMID 36560732, 2022). "TMPRSS2, a cell surface protease regulated by androgens and commonly upregulated in prostate cancer (PCa), is a necessary component for SARS-CoV-2 viral entry into respiratory epithelial cells." (PMID 35657341, 2022). "In the case of prostate cancer, the TMPRSS2–ERG fusion leads to upregulation of the ETS transcription factor ERG, which drives invasion and migration of prostate cancer cells and restricts their differentiation capacity." (PMID 35954292, 2022). "Recently, HAI-1 and HAI-2 have been identified as endogenous TMPRSS2 inhibitors in prostate cancer cells." (PMID 36309092, 2022). "Subsequent studies revealed that overexpression of TMPRSS2 activates the TTSP matriptase in prostate cancer cells, which in turn activates PAR-2." (PMID 35163273, 2022). "Rearrangements between TMPRSS2, encoding an androgen-regulated protease, and ERG, an ETS transcription factor, are among the most common somatic alterations in human prostate cancers." (PMID 35104804, 2022). "In general, several lines of evidence suggest an involvement of TMPRSS2 activity in the progression of prostate cancer." (PMID 35163273, 2022). "Detection of the well-established fusion gene TMPRSS2-ERG in prostate cancer using targeted deep DNA-sequencing data has 91% concordance manually curated calls of the fusion." (PMID 35251131, 2022). "In this regard, though several data documented an androgen-mediated upregulation of TMPRSS2 in the prostate cancer cells, only a slight increase in TMPRSS2 transcript has been found in lung males compared to females." (PMID 35712238, 2022). "The gene fusion product transmembrane-protease-serine-2 (TMPRSS2)-ETS-related gene (ERG) as a result of chromosomal translocation is observed in 20 to 50% of prostate cancer patients with different ethnicities." (PMID 35547880, 2022). "Consistent with the role of TMPRSS2 in prostate cancer, Lucas and colleagues reported a reduction in prostate cancer metastasis upon treatment with BHH in vitro and in vivo." (PMID 35163273, 2022). "ERG is also known to be fused to transmembrane protease serine 2 (TMPRSS2) in prostate cancer cells, resulting in ERG overexpression." (PMID 35723257, 2022). "We ranked our tools based on their accuracy to detect the fusion TMPRSS2:ERG in each of the prostate cancer cell lines, together with ease of use and the total time required." (PMID 35625354, 2022). "We detected a higher level of TMPRSS2 in the tumors, presumably because the activated AR in prostate cancer directly bind to its promoter region." (PMID 36088396, 2022). "An initial study (n = 64 Black men) detected TMPRSS2-ERG gene fusions in prostate cancers from 50% of White men, compared with 31.3% of Black men and 15.9% of Japanese men." (PMID 35104804, 2022). "Previous studies found that ~55% of prostate cancer patients have ERG overexpression driven by fusion of the ERG gene with androgen response genes such as TMPRSS2." (PMID 36579559, 2022). "We further analyzed TMPRSS2 mRNA expression in pan-cancers and found that TMPRSS2 mRNA expression was highest in prostate cancer with 234.4 fragments per kilobase of exon model per million mapped fragments (FPKM)." (PMID 36364238, 2022). "The overexpression of ERG can mostly be attributed to the fusion of the ERG and transmembrane serine protease 2 (TMPRSS2) genes, and this fusion is estimated to represent about 85% of all gene fusions observed in prostate cancer." (PMID 35563163, 2022). "The role of TMPRSS2 in COVID-19 and prostate cancer is widely discovered, but in other cancers is rarely reported." (PMID 35558557, 2022).
prostate carcinoma (continued). "The fusion of E-26 transformation-specific-related gene (ERG) and transmembrane serine protease 2 (TMPRSS2) genes is the most common genomic change in prostate cancer." (PMID 35223512, 2022). "The results showed that TMPRSS2 was highly expressed in bladder cancer, breast cancer, kidney cancer, leukemia, liver cancer, melanoma, and prostate cancer." (PMID 35558557, 2022). "T:E fusion-positive prostate cancer was obtained by considering fusions of exon 1 of TMPRSS2 to exon 4 or exon 5 of ERG (n = 86) because exon 4 or exon 5 of ERG are the most abundant breaking sites, generating T:E fusions." (PMID 36579559, 2022). "In the future, we will further explore the difference between the TMPRSS2: ERG fusion gene and the TMPRSS2 gene through basic and clinical research, as well as the prognostic role in prostate cancer." (PMID 34951103, 2022). "TMPRSS2 has been intensively studied in prostate cancer as it is an AR-up-regulated gene, which occurs as a gene fusion of its promoter with ETS family transcription factors in over two-thirds of prostate cancer patients." (PMID 35328625, 2022). "Our results partially differ from other studies reporting a transient interaction of the SWI/SNF complex with the EWSR1‐FLI1 fusion oncoprotein in Ewing sarcoma and TMPRSS2‐ERG in prostate cancer." (PMID 35182012, 2022). "TMPRSS2:ERG (T:E) fusion is most frequently found in prostate cancer, and its oncogenic role and regulating molecular mechanisms have been well studied." (PMID 36579559, 2022). "TMPRSS2 interacts with the tumor microenvironment and promotes prostate cancer cell invasion, tumor growth, and metastasis." (PMID 35558557, 2022). "Concerning this, TMPRSS2 has received a lot of attention in the context of prostate cancer, it is expressed abundantly and increases the responses to the androgens through direct transcriptional regulation of androgen receptors (AR)." (PMID 35812188, 2022). "Accumulating evidence indicates that TMPRSS2 plays an important role in the oncogenesis of prostate cancer." (PMID 35017320, 2022). "SLC45A3:ERG (S:E) fusion is found in approximately 6% of ERG fusion prostate cancer, and concurrent TMPRSS2 and SLC45A3 fusions to ERG are found in 11% of ERG fusion-positive cancer." (PMID 36579559, 2022). "The best known fusion genes associated with prostate cancer involve ETS transcription factor family members and the androgen-regulated promotor TMPRSS2 (TMPRSS2:ERG, TMPRSS2:ETV1, and TMPRSS2:ETV4)." (PMID 35625354, 2022). "The relatively high expression levels in prostate tissue and the identification of TMPRSS2 substrates in prostate cancer models argue for a potential role of TMPRSS2 in regular prostate function." (PMID 35163273, 2022). "Since then, due to the high expression of the TMPRSS2 gene in the prostate, research on TMPRSS2 has mainly focused on the related diseases of prostate cancer." (PMID 35281819, 2022). "A recent study identified HAI-2, a cognate inhibitor of TMPRSS2, as mediating the proteolytic activity of TMPRSS2 to inhibit the invasion and metastasis of prostate cancer." (PMID 35017320, 2022). "TMPRSS2:ERG fusions are a common genomic alteration in prostate cancer; however, variations in its incidence have been extensively observed." (PMID 35625354, 2022). "CTCs isolated from prostate cancer patients can express PSA and show molecular characteristics of prostate cancer such as AR copy number gain, PTEN loss and TMPRSS2-ETS gene fusion." (PMID 35715640, 2022). "TMPRSS2 expression was highest in prostate cancer followed by urothelial cancer, renal cancer, and pancreatic cancer." (PMID 36364238, 2022).
prostate carcinoma (continued). "In vitro studies using an androgen-dependent prostate cancer cell line identified protease-activated receptor-2 (PAR-2) as a potential endogenous substrate for TMPRSS2." (PMID 35163273, 2022). "For the targeted deep-sequencing of prostate cancer patients, detection of the TMPRSS2-ERG fusion, which is the most frequent chimeric alteration in prostate cancer, is 91% concordant with a manually curated procedure based on four other methods." (PMID 35251131, 2022). "Alternative splicing in AR and gene fusion events for TMPRSS2 with ETS-family members are involved in prostate cancer." (PMID 35328625, 2022). "In accordance with this, the Notch pathway has been found activated in ERG-inducible LNCaP TMPRSS2:ERG (T2E) prostate cancer cells, as demonstrated by the upregulation of direct Notch pathway target genes such as HES1." (PMID 35954292, 2022). "In prostate cancer, the TMPRSS2‐ERG fusion protein was also shown to interact with BRD4 and with SWI/SNF." (PMID 35182012, 2022). "For example, the transcription factor SOX2 binds to the promoter region of β-catenin to mediate EMT in the DU145 prostate cancer cell line, which lacks a TMPRSS2-ERG translocation, and also in breast cancer cell lines." (PMID 34685470, 2021). "The well-known TMPRSS2 gene fusions in prostate cancer were also detected in CCLE data by RNA-seq STAR-fusion algorithm, in VCAP and NCIH660 cell lines, but these cell lines did not have corresponding WGS data for SV calling." (PMID 33743584, 2021). "More recently, a novel fusion event was reported in about 1% of prostate cancer cases, juxtaposing exons 1 or 2 of TMPRSS2 to exon 2 of the SMAD inhibitor and oncogenic factor SKIL and leading to its overexpression." (PMID 33634124, 2021). "Overall, degron loss contributes to many of the most highly recurrent gene fusions specific to particular cancer types, including PML-RARA in acute myeloid leukemia (LAML), EGFR-SEPT14 in gliomas, and TMPRSS2-ERG in prostate cancers." (PMID 34795215, 2021). "TMPRSS2 is capable of increasing the metastatic spread of prostate cancer by activating the Hepatocyte Growth Factor (HGF)." (PMID 34399734, 2021). "While TMPRSS2-ERG activates NO-cGMP signaling in prostate cancer cells, sGC inhibitor treatment repressed tumor growth in TMPRSS2-ERG-positive VCaP xenograft models and acted in synergy with enzalutamide, the potent AR antagonist." (PMID 33634124, 2021). "TMPRSS2 is involved in several prostate cancers and is highly expressed in the prostate, where it is highly regulated by androgens and/or androgen receptors." (PMID 34832534, 2021). "Also, a study conducted on 214 patients with prostate cancer demonstrated that the T allele of this variant, which is associated with the presence of Met amino acid, was associated with TMPRSS2-ERG fusion and, thus, might be important in prostate cancer pathogenesis." (PMID 34001248, 2021). "For example, TMPRSS2 protein expression is upregulated by androgens in prostate cancer cells and prostate tumors." (PMID 34575910, 2021). "About 50% of prostate cancer (PCa) tumors are TMPRSS2:ERG (T2E) fusion-positive (T2E+), but the role of T2E in PCa progression is not fully understood." (PMID 33669024, 2021). "The mRNA expression level of TMPRSS2 is robustly increased in prostate cancer in response to androgen stimulation." (PMID 34001144, 2021). "In contrast, we observed the opposite phenotypic and molecular changes in VCaP human prostate cancer cells harboring the recurrent TMPRSS2-ERG fusion." (PMID 33531470, 2021).
prostate carcinoma (continued). "Transmembrane protease/serine subfamily member 2 has been widely studied in the context of prostate cancer, where, it is highly expressed, and TMPRSS2 expression is increased in response to androgens through direct transcriptional regulation by the AR." (PMID 34803967, 2021). "Markers selected for the model include well-known genes associated with prostate cancer and proven in other diagnostic tests, such as PCA3, HOXC6, and the TMPRSS2/ERG gene fusion." (PMID 33925381, 2021). "Data from prostate cancer research has demonstrated the androgen receptor as a regulator of TMPRSS2, capable of increasing the expression of this gene." (PMID 33179220, 2021). "Patients, particularly with prostate cancer, have higher expression of TMPRSS2 as compared to patients with renal, lung, colorectal, or pancreatic cancers, while other cancers have no significant expression of TMPRSS2." (PMID 33912588, 2021). "Recently, higher levels of carnitines were detected in prostate cancer tissue with presence of the gene fusion TMPRSS2-ERG (transmembrane protease, serine 2—ETS-related gene), a marker associated with shorter recurrence-free survival and cancer specific death." (PMID 33514438, 2021). "Nearly half of patients with prostate cancer have a translocation between the TMPRSS2 locus and ERG or another ETS family transcription factor, which places the transcription factor under the control of androgens." (PMID 34685470, 2021). "TMPRSS2 is also a widely studied androgen-regulated gene in prostate tissue, contributing to prostate cancer pathogenesis by way of aberrantly driving oncogene expression." (PMID 34045511, 2021). "Hormonally regulated TMPRSS2-ERG gene fusion prevalence is higher in European males which have primary prostate cancer (50%) in comparison with Asian or Black males." (PMID 34803443, 2021). "Mouse experiments showed that prostate cancer metastasis is more likely to be promoted in the presence of TMPRSS2." (PMID 34001144, 2021). "Similar results were shown by FISH analysis of TMPRSS2-ERG rearrangements in multifocal prostate cancers." (PMID 33634124, 2021). "The origins of the most common fusion in prostate cancer, TMPRSS2/ERG is accredited to intronic AR binding in combination with DNA damage or inflammatory signaling." (PMID 34409300, 2021). "For example, the TMPRSS2 plays a role in the pathophysiology of prostate cancer by interacting with the oncogenic transcription factor ERG." (PMID 33179220, 2021). "For example, when compared to prostate cancers from predominantly White men, prostate cancers from Black men contain fewer TMPRSS2-ERG fusions, fewer PTEN deletions, and more SPOP mutations." (PMID 34191807, 2021). "Further, the results demonstrated that Tmprss2 was significantly involved in the “prostate cancer” KEGG pathway, as well as in the “import into cell” term with Per2, Atp1a1, and Arrb1 (GO:0098657, FDR = 3.39 × 10−5)." (PMID 34834564, 2021). "We show here that treatment with the antiandrogen enzalutamide—a well-tolerated drug widely used in advanced prostate cancer—reduces TMPRSS2 levels in human lung cells and in mouse lung." (PMID 34210968, 2021). "The TMPRSS2:ERG fusion is present in the VCaP prostate cancer cell line and has been more recently well-characterized in this model." (PMID 33634124, 2021). "Due to its high frequency in prostate cancer cases, the TMPRSS2:ERG fusion is considered to be relevant for the disease." (PMID 33634124, 2021). "Especially, despite a lot of effort, the field has yet to pinpoint why and how TMPRSS2-ERG fusion is an early event in prostate cancer development, yet the most significant functions of it seem concentrated in the phase of metastatic disease." (PMID 33634124, 2021). "According to the Human Protein Atlas, ACE 2 and TMPRSS2 are highly expressed in prostate cancer and on tumor as well as normal colorectal epithelial tissues." (PMID 34399734, 2021).